CRP (C-reactive protein)
Diseases named in the same sentence as CRP in open-access papers (continued):
Sharing a sentence is not in itself a finding about the gene and the disease.
infection (continued). "Individuals who experienced various wound problems (for example, an infection) had CRP levels that were, on average, greater (~35 mg/L) than those participants who did not experience any issues (~9 mg/L)." (PMID 38392639, 2024). "The inflammatory markers were elevated (erythrocyte sedimentation rate (ESR): 132mm/hr and C-reactive protein (CRP): 23.7 mg/dL) indicating an ongoing severe infection or inflammation or tissue damage." (PMID 39479107, 2024). "It has been concluded that CRP can be used as an effective indicator to identify the degree of infection between DFG patients and patients with different severity of foot ulcers, and can directly reflect the level of inflammation." (PMID 38725871, 2024). "In IAI group, CRP levels elevated at the early stage of anti‐infection (T1) and remained at high level throughout the subsequent anti‐infection courses (24–72 h)." (PMID 38967137, 2024). "C-reactive protein (CRP) is an acute-phase protein usually elevated in response to inflammation or infection." (PMID 38835341, 2024). "When it comes to the biochemical markers of stress, the high CRP levels are connected with a state of acute injury, tissue damage, infection or inflammation." (PMID 39199534, 2024). "CRP remains an essential biomarker used in clinical practice to monitor infection, inflammation, and autoimmune diseases." (PMID 39726515, 2024). "Elevated NLR and CRP levels indicate infection severity and serve as valuable tools for monitoring treatment response and predicting patient outcomes." (PMID 39205364, 2024). "Our identification of novel models using PCT and CRP for predicting infection, and PCT and CRS for predicting severe infection, offers potential to guide therapeutic decisions and enhance the efficacy of CAR-T cell therapy in the future." (PMID 38956649, 2024). "CRP is a protein induced by IL-6 in the liver, and it is evidenced by sensitive biomarkers of inflammation, infection, and tissue damage in response to exertion." (PMID 39595661, 2024). "Due to symptom improvement and CRP reduction, the patient discontinued Teicoplanin and Cefoperazone Sulbactam and switched to Meropenem for infection treatment, subsequently Paxlovid and methylprednisolone were also discontinued." (PMID 39776845, 2024). "Extensive prospective studies have identified CRP as a critical biomarker for infections, inflammation, cardiovascular diseases, atherosclerosis, and related conditions." (PMID 39337259, 2024). "Analysis of the serial samples of the patients revealed that MVP had a remarkable fall during the first four days of infection, as a response to the antibiotic treatment, while CRP levels had a lower, insensitive fall." (PMID 39338437, 2024). "The parameters CRP and N% are closely related to infection, and they increase significantly when there is infection." (PMID 39470556, 2024). "Biomarkers such as procalcitonin (PCT) and C-reactive protein (CRP) are critical in assessing the body's response to these infections." (PMID 39403639, 2024). "CRP is an acute-phase reactant produced by the liver in response to inflammation, often following an infection." (PMID 39726515, 2024). "CRP can be detected six to eight hours after the start of infection, reaching peak concentrations 36–50 h post-burn." (PMID 39716257, 2024). "In individuals with ongoing infection or inflammation (symptoms or elevated C-reactive protein [CRP]), the measurement of ferritin should optimally be postponed until inflammation has subsided." (PMID 38370116, 2024). "CRP levels, serving as an indicator of infection, exhibited a notable increase in the positive control group (9 mg/L) compared to the normal (<5 mg/L)." (PMID 38911027, 2024). "Repeat blood investigations revealed a further rise in infection markers, with a CRP level of 184 mg/L (reference range: <5 mg/L) and a WBC count of 14.0 × 109/L (reference range: 4.0-11.0 × 109/L)." (PMID 39629288, 2024).
infection (continued). "Particular consideration was given to the fact that there are a number of tests that have a very high sensitivity with low specificity (C-reactive protein, scintigraphy) and make an infection probable but cannot prove an infection overall." (PMID 38667027, 2024). "In the last case, the pH was 7.91 in an infection of a knee joint with Streptococcus agalactiae, with a CRP of 46.5 mg/L." (PMID 38337382, 2024). "PCT increases earlier than CRP in the presence of an active infection and decreases quickly when the infection is controlled, allowing monitor antibiotic response, potentially reducing antibiotic treatment indication and length." (PMID 38581075, 2024). "PCT and CRP were the most frequently studied biomarkers in patients with infections between 2009 and 2019." (PMID 38609858, 2024). "His discovery of CRP and the immunogenic properties of pneumococcal polysaccharides advanced the science of infection and immunity and laid the foundation for modern clinical diagnostics and vaccine development." (PMID 39726515, 2024). "As such, elevated CRP level has been frequently used as an indicator for on-going infection/inflammation." (PMID 38511149, 2024). "CRP is an acute-phase protein that the liver synthesizes in response to inflammation, particularly infection." (PMID 39575025, 2024). "Previous study has delineated that CRP remains at high level during anti‐infection process and cannot predict antimicrobial efficacy." (PMID 38967137, 2024). "Antibiotic therapy’s duration of the first infection episode was observed to show similar outcomes for both CRP and PCT groups." (PMID 38254218, 2024). "The sensitivity of CRP as a marker for infection has been reported to be the highest among all parameters." (PMID 39539898, 2024). "This new definition proposed three groups (‘infection unlikely’, ‘likely’ and ‘confirmed’) and has retained only CRP as serum parameter, making it an ‘infection likely’ criteria." (PMID 39407776, 2024). "Within 72 h of anti‐infection, the predictive ability of serum IL‐6 and CRP increases with the prolongation of antibiotic time." (PMID 38967137, 2024). "CRP: High levels of serum C reactive protein [CRP] result from liver inflammation and infection, and are a marker of filovirus infection." (PMID 39205155, 2024). "The acute response protein CRP can be used as an indicator to evaluate the degree of inflammatory response and infection." (PMID 39180109, 2024). "CRP is a laboratory chemical marker that is routinely used in clinical work to detect inflammation and infection." (PMID 39001486, 2024). "A CRP level can rise dramatically in response to injury, infection, and inflammation, serving both as a marker and an active participant in the inflammatory process." (PMID 39594253, 2024). "For identifying the infection, some factors such as fever, CRP test results, CSF parameters (leukocyte count, glucose level, and CSF culture results) should be considered to prevent misdiagnosis." (PMID 39810804, 2024). "For patients with cancer, multiple studies have found that PCT serves as a more reliable indicator of infection than other biochemical markers, including C-reactive protein (CRP) and white blood cell count (WBC)." (PMID 39609770, 2024). "C-reactive protein (CRP) is an acute-phase protein produced by the liver in response to infection and during chronic inflammatory disorders." (PMID 38895111, 2024). "Laboratory tests, such as elevated inflammatory markers like C-reactive protein and erythrocyte sedimentation rate, can aid in confirming the presence of infection." (PMID 39165660, 2024). "Given its ability to reflect both the presence and severity of inflammation or infection, the cost-effective daily monitoring of CRP proves invaluable for the screening and management of these diseases." (PMID 39337259, 2024).
infection (continued). "CRP is one of the acute phase reaction proteins and one of the most commonly used indicators of infection, and its level reflects the strength of the inflammatory storm in the body." (PMID 38360539, 2024). "These previous studies suggest a relationship between a CRP threshold and the development of a post-operative infection across surgical approaches and comorbidity." (PMID 38184537, 2024). "Further longitudinal studies are needed to understand the dynamic changes in arachidonic acid, IL-6, and CRP levels during infection and recovery." (PMID 39066228, 2024). "The increase in inflammatory markers such as ferritin and CRP noted in this patient suggests the presence of severe infection." (PMID 39598252, 2024). "CRP and other infection response markers rise and recover differently depending on clinical syndrome and pathogen involved." (PMID 38599549, 2024). "C-reactive protein (CRP) is an acute-phase reaction protein predominantly synthesized in the liver in response to acute injury, infection, or other inflammatory stimuli." (PMID 39726534, 2024). "Among adults, M. pneumoniae affected more females, and the infection presented with more severe clinical, radiological, and biochemical manifestations, as indicated by the levels of C-reactive protein." (PMID 38534697, 2024). "C-reactive protein (CRP) is the most commonly used clinical marker for assessing the grade of infection, tissue damage, and inflammation." (PMID 38430452, 2024). "In the SILC group, three children exhibited postoperative abdominal infection, presenting with hyperpyreia and increased CRP levels on the 3rd day after surgery, which recovered after one week of anti-infection treatment with cefoperazone." (PMID 39363967, 2024). "High CRP levels in deep neck infections suggest significant inflammation, correlating with infection severity and leading to prolonged hospitalization for intensive treatment and recovery." (PMID 39205364, 2024). "In a multivariate analysis ECOG status, RBC transfusion dependency, IPSS-R score, and CRP concentration were statistically significant for infection development (p < 0.05)." (PMID 38939343, 2024). "MVP levels significantly decreased during the first four days of infection in response to antibiotic treatment, while CRP levels showed a less-sensitive decline." (PMID 39338437, 2024). "We assessed routine indicators of infection in the enrolled patients, including CRP, PCT, IL-6, and SAA levels." (PMID 39533550, 2024). "The biomarkers, including PCT, IL-6, CRP, and their combination, can help confirm a diagnosis of infection." (PMID 38956649, 2024). "The higher the CRP concentration and therefore the more severe the infection, the higher the Ang-II concentrations were." (PMID 39595003, 2024). "We observed significant differences (p < 0.01) between the groups for CRP and IL-6 levels that were higher in moderate/severe disease than in mild infection." (PMID 39518479, 2024). "The elevated level of CRP indicates the presence of infection, especially bacterial pathogen or inflammatory diseases, particularly cardiovascular diseases." (PMID 38698064, 2024). "In particular, the prognostic role of GDF-15 was more reliable in the early phase of the infection, when compared with other inflammatory biomarkers, including CRP, ferritin, D-dimer, and IL-6." (PMID 38700782, 2024). "Biochemical markers such as procalcitonin and CRP exhibit elevated levels in early and late infection periods, potentially indicating ongoing inflammation." (PMID 38398027, 2024). "In LRTIs, CRP levels below 20 mg/L suggest a self-limiting infection, presumably of viral origin, while levels above 100 mg/L indicate a severe bacterial infection." (PMID 39407829, 2024). "On day two of admission, there was an increasing trend in the patient's inflammatory and infection markers (white blood cell count and CRP), suggesting a possible persistent or worsening inflammatory response." (PMID 39483585, 2024).
infection (continued). "Blood tests were indicative of an infection: white blood cells count=18 300 cells mm−3, elevated neutrophils with a left shift, and C-reactive Protein (CRP)=130 mg l−1." (PMID 39280083, 2024). "During episodes of infection or inflammation, CRP levels can increase dramatically, by up to 1000-fold." (PMID 39337259, 2024). "These viral CP (or MCP) and CrP are in charge of the infection of their hosts; however, their role in infection is still poorly understood." (PMID 38598600, 2024). "The inflammatory markers C-reactive protein (CRP) and procalcitonin were only substandard or mildly elevated, and presepsin, which more acutely reflects infection, was substandard." (PMID 38978900, 2024). "The low-cost daily monitoring of C-reactive protein (CRP) levels is crucial for screening acute inflammation or infections as well as managing chronic inflammatory diseases." (PMID 39337259, 2024). "Temperature (‘apyrexial’/‘pyrexial’) was consistently communicated (X11), but infection-related biomarkers such as white cell count (WCC) or C-reactive protein (CRP) and microbiological culture results were rarely mentioned." (PMID 39925665, 2024). "Endogenous blood biomarkers such as white blood cell count, erythrocyte sedimentation rate, C-reactive protein, and procalcitonin are regularly used as indicators of the host response to infection and therefore a relative measure of infection severity." (PMID 37843549, 2024). "CRP, another synovial biomarker, is a prominent inflammation marker and has long been utilized as an indicator of infection within the field of orthopedic surgery." (PMID 39285443, 2024). "CRP, an acute-phase protein synthesized by the liver, exhibited increased levels in response to inflammation or infection." (PMID 39347502, 2024). "Small sample size, distinct waves studied, transversal versus longitudinal analysis, period post infection of the study can yield different results especially with inflammatory biomarkers such as CRP." (PMID 39478809, 2024). "CRP, a recognized biomarker for inflammation, is often elevated following surgery in instances of complications such as infections or anastomotic leaks." (PMID 39598263, 2024). "After tissue damage, the liver produces CRP, an acute phase protein that can indicate infection or inflammation." (PMID 38910781, 2024). "The main criteria for diagnosing infection in all neonates was elevated C-reactive protein above 10 mg/L." (PMID 38629000, 2024). "ESR and CRP are among the most common serum markers used to seek infection because of their ease of processing and rapid results." (PMID 39493345, 2024). "It is reassuring that our data-driven approach identified CRP, leukocyte count, HR, and diastolic BP among the informative ML features which are classical parameters for infection diagnosis." (PMID 37851190, 2024). "Laboratory tests for infection markers are also indicated, such as erythrocyte sedimentation rate, C-reactive protein, and procalcitonin level (recommendation class IIb, level of evidence C)." (PMID 38803655, 2024). "Third, as supported by increasing evidence, inflammatory factors, such as CRP, are produced by hepatocytes after trauma, infection, and cancer; moreover, they can also be produced by cancer cells." (PMID 38172843, 2024). "Other studies identified MELD score, lactates, infection, albumin, and CRP and CRP/albumin ratio as independent predictors of in-hospital mortality." (PMID 39594174, 2024). "CRP is an acute-phase protein that is produced by the liver in a state of infection, inflammation, or malignancies." (PMID 39519417, 2024). "CRP plays important roles in protection against infection, clearance of damaged tissue and regulation of the inflammatory response, because it acts as an opsonin by binding to bacteria and free DNA." (PMID 38951921, 2024).
infection (continued). "Neutropenic patients should be closely monitored for early signs of infection, such as febrile episodes, changes in clinical status, or abnormal laboratory results like elevated CRP and PCT levels." (PMID 39698316, 2024). "The use of serum biomarkers, such as IL-6, C-reactive protein, ferritin, d-dimer, white blood cell count, and lymphocyte count, is crucial for staging the infection." (PMID 39540054, 2024). "The remaining 39 patients (39%) tested positive for CRP, suggesting potential inflammation or infection." (PMID 39118076, 2024). "The Academy of Orthopaedic Surgeons (AAOS) developed an algorithm for diagnosing perprosthetic infections in 2010, utilizing C-reactive protein (CRP) with a threshold of 10 mg/L as a screening parameter." (PMID 38667027, 2024). "aPreoperative finding of infection: preoperative clinical signs (swelling, sinus tract, redness, or drainage), positive erythrocyte sedimentation rate, or positive C-reactive protein." (PMID 39411639, 2024). "But in the positive control group, WBC and CRP-q levels increased significantly, which indicated infection." (PMID 38911027, 2024). "C-reactive protein (CRP) is an acute phase reactant to inflammation or infection and is widely used as a biomarker in both clinical and research settings." (PMID 39209009, 2024). "C-reactive protein (CRP), an acute-phase protein, is produced during infection, inflammation, and tissue injury, and it participates in the body’s non-specific inflammatory responses." (PMID 38791032, 2024). "As expected, we found that their levels were similar (SAA1 and SAA2) or increased (CRP) to a greater extent in patients with more severe infection symptoms (NIH-2 group) during infection compared to those with mild to moderate characteristics (NIH-1 group)." (PMID 39183264, 2024). "CRP, an acute-phase protein predominantly secreted by hepatocytes, can also be produced by neurons in response to infection (Yasojima, Schwab, McGeer, & McGeer, 2000)." (PMID 38445386, 2024). "As found in our study, a relationship was observed between CRP and ferritin as both increased during an infection." (PMID 38398719, 2024). "CRP, an acute phase protein, rises in response to infection and inflammation, likely reflecting a more severe inflammatory response to pulmonary infection, leading to poorer clinical outcomes." (PMID 39202627, 2024). "The highest levels of C-reactive protein and procalcitonin observed during the infection course were 167.9 mg/L (mean, standard deviation [SD] 103.0) and 2.0 ng/mL (median, IQR 0.7–7.5), respectively." (PMID 39061281, 2024). "CRP is a hepatic acute-phase reactant that is produced in response to tissue damage, inflammation, and infection." (PMID 39358806, 2024). "Another concern is that the usefulness of PCT and other inflammatory markers, such as CRP and interleukin 6, as biomarkers for infection has long been debated because of their low specificity and sensitivity." (PMID 39305165, 2024). "CRP levels tend to increase following infection, and as a result are generally employed as an indicator of severity of infection." (PMID 39467995, 2024). "The study highlighted that CRP is a sensitive marker for inflammation and infection, with levels peaking within the first 48 h postoperatively and gradually declining thereafter." (PMID 39708150, 2024). "CRP is a traditional marker of infection and is often used to diagnose febrile UTIs and evaluate treatment effectiveness." (PMID 39334613, 2024). "The acute-phase response is an innate, immune-mediated inflammatory process accompanied by elevation of certain acute-phase proteins, such as C-reactive protein (CRP) or α-1-acid glycoprotein (AGP) in response to infection, inflammation, injury, or trauma." (PMID 39700205, 2024). "Regarding CRP rapid testing, we recognize that elevated CRP levels can signal systemic inflammation in conditions beyond infections, such as inflammatory disorders." (PMID 39407829, 2024).